CXCL9 (C-X-C motif chemokine ligand 9)
Diseases named in the same sentence as CXCL9 in open-access papers (continued):
Sharing a sentence is not in itself a finding about the gene and the disease.
lung cancer (50 papers, 2012 to 2025). A malignant neoplasm involving the lung. "Only CXCL9 showed moderate diagnostic potential for lung cancer, and a previous study showed similar results in lung cancer patients." (PMID 34501934, 2021). "The results showed that CXCL9 was associated with lung cancer risk in the replication study, and remained associated with it more than 6 years prior to diagnosis in pooled analyses." (PMID 27726306, 2016). "Increased blood levels of CXCL9 have been associated with an increased risk of lung cancer." (PMID 34501934, 2021). "Cxcl9/Cxcl10-engineered dendritic cells were reported to promote T cell activation and enhance immunotherapy in lung cancer, highlighting the critical role of DCs in cancer." (PMID 40282557, 2025). "These contrasting results highlight the need for additional work to address the contributions of the CXCL9/CXCL10-CXCR3 to lung cancer immunity." (PMID 39114657, 2024). "The antitumor efficacy of in situ vaccination with CXCL9/10-DC was assessed in multiple syngeneic murine models of lung cancer." (PMID 38518770, 2024). "In situ vaccination with CXCL9/10-DC provided broad antitumor efficacy in multiple murine models of lung cancer and augmented the effectiveness of anti-PD-1 therapy in murine models of LKB1-deficient NSCLC." (PMID 38518770, 2024). "By enhancing the infiltration of CD8 + T and CD4 + T cells in the TME, Cryptotanshinone accelerates anti-PD-L1 activity in a lung cancer model with high expression of chemokine (C-X-C motif) ligand 9 (CXCL9), CXCL11, and granzyme B +." (PMID 37210537, 2023). "C-X-C motif chemokine ligand 9 (CXCL9) is a small cytokine belonging to the CXC chemokine family, and it is associated with hypertension, diabetes, obesity, and lung cancer." (PMID 36685671, 2023). "There was a higher CXCL9/10 level in the lung cancer patient plasma than the healthy control, and surprisingly, CXCL9/11 were independent prognostic factors for poor survival." (PMID 36429101, 2022). "Antibiotic treatment in a preclinical lung cancer model significantly decreased CXCL9 in the lung TME, resulting in reduced sensitivity to anti–PD-1 antibody, which was reversed by CXCL9 induction in tumor cells." (PMID 35389889, 2022). "In a prospective study, blood samples were collected from lung cancer patients and healthy controls in order to monitor the plasmatic chemokine levels of CXCL9/10/11 and IFNγ which are known to promulgate T-cell efficacy." (PMID 36429101, 2022). "We also demonstrated that CXCL9 increased in the serum of patients with lung cancer (n = 5, 1491 ± 663 pg/mL) compared to that in healthy volunteers (n = 605 ± 381 pg/mL) (p = 0.083)." (PMID 34680466, 2021). "In this study, we found that irradiation-induced IFNα and CXCL9 in lung cancer A549 cells result in the increase of CD8+ T cell motility homing to tumors." (PMID 34680466, 2021). "Based on ROC analysis, the AUC (95% CI) of CXCL9 was 0.84 (0.80–0.88) for differentiating lung cancer patients from controls." (PMID 34501934, 2021). "Oral gavage of the responder taxa significantly improved the patient response to erlotinib and induced the expression of CXCL9 and interferon-γ in a murine lung cancer model." (PMID 35004303, 2021). "The area under the curve (AUC) (95% CI) of CXCL9 was 0.83 (0.80–0.89) for differentiating lung cancer patients from controls." (PMID 34501934, 2021). "The observation indicated that nonCD8+ PBMCs were continually stimulated by the tumor cells in the patients with lung cancer, resulting in the secretion of CXCL9 in the serum." (PMID 34680466, 2021). "CCL1, CCL21, IP-10, CCL8 and CXCL9 levels were much higher in pleural effusions from patients with TP compared with lung cancer patients." (PMID 23028695, 2012). "Moreover, in “cold-type” lung cancer, epigenetic regulators can activate chemokines such as CXCL9 and CXCL10, transforming it into a “hot-type” tumor and significantly enhancing the response rate to PD-1/PD-L1 inhibitors." (PMID 41394878, 2025).
lung cancer (continued). "CXCL9 is expressed by M1 tumor-associated macrophages and recruited CD8+ tissue-resident memory T cells, and increases in both immune cell types in tumors are associated with better overall lung cancer survival." (PMID 37374908, 2023). "Another study, which included 53 lung cancer patients, indicated that the subjects who developed irAEs possessed lower baseline levels of CXCL9, CXCL10, CXCL11 and CXCL19, as well as a greater increase in CXCL9 and CXCL10 at post-treatment, compared with those without irAEs." (PMID 36949956, 2023). "This study found that RT induced IFNs and CXCL9/10 expression in the RT-treated lung cancer cells." (PMID 36688994, 2023). "To investigate this, we developed a murine lung cancer model and evaluated whether dysbiosis reduced the CXCL9 level in BALF and the antitumor effect of anti–PD-1 antibodies in vivo." (PMID 35389889, 2022). "In addition, CXCL9 and CXCL10 decreased in a patient’s nonCD8+ PBMCs but CXCL9 concentration increased in the sera of patients with lung cancer." (PMID 34680466, 2021). "In our historical cohort of patients with lung cancer (n=393), whose tumors were preclassified on the basis of the density of cells expressing CXCL9 (M1hot, M1intermediate, M1cold), we determined the density of cells expressing CD103, a marker of TRM cells (TRMhigh, TRMint or TRMlow)." (PMID 32699181, 2020). "Their research suggested that CXCL9 has an etiologic role in lung cancer." (PMID 27726306, 2016). "However, macrophages in lung cancer tissues expressed high levels of CXCL9 and CXCL10." (PMID 35069521, 2021). "In summary, we demonstrated that TPE induces Arg-1 M2 polarization of MФ via CXCL9/CXCL10, which promotes the progression of lung cancer via autophagy/E-cadherin signaling." (PMID 38720340, 2024). "Despite the important role of the CXCL9/CXCL10-CXCR3 axis in NK/DC/CD8+ T cell crosstalk, this pathway has been insufficiently studied in the context of lung cancer." (PMID 39114657, 2024). "Cochrane’s Q test did not provide evidence of heterogeneity between CCL14 (p = 0.916), CCL19 (p = 0.446), CCL20 (p = 0.130), CCL21 (p = 0.878), CCL27 (p = 0.762), CXCL9 (p = 0.340) and CXCL13 (p = 0.770) and lung cancer." (PMID 38075694, 2023). "The serum levels of CXCL9, CXCL10, and CXCL 11 were significantly correlated with one another in all lung cancer and NSCLC patients, but the degree of correlation was relatively weak." (PMID 34501934, 2021). "Our results support the notion that CXCL9 and CXCL10 are also critical in the context of lung cancer immunotherapy." (PMID 34206510, 2021). "Here, we evaluated the clinical implications and prognostic significance of IFN-γ-inducible chemokines by measuring levels of CXCL9, CXCL10, and CXCL11 and their inducer IFN-γ in the peripheral blood of patients with lung cancer." (PMID 34501934, 2021). "Meanwhile, we also demonstrated that decreased CXCR3, a receptor for CXCL9/10, in the CD8+ T cells of patients with lung cancers exhibited lower motility compared to healthy CD8+ T cells." (PMID 34680466, 2021). "Then, we further confirmed that ICT treatment increased CXCL9 and CXCL10 secretion in the mouse LLC and the human H1975 lung cancer cell lines by RT-PCR." (PMID 33460401, 2021). "Again, many of the immune-modulatory genes differentially expressed in the mouse model were site-specifically recapitulated, e.g., higher CCL2, CXCL5, CXCL9, CXCL11, CXCL14, CXCL17, and IDO1 in lung cancers and higher CXCL12, FGL1, and LAG3 in liver cancers." (PMID 33985562, 2021). "The combination of IL-12, IFN-γ, CXCL9 and CXCL10 has been shown to be strongly correlated with recruitment of CD8+ T cells in the tumor, in colorectal and lung cancers." (PMID 32033490, 2020). "Oral gavage of these responder bacteria significantly increased the efficacy of erlotinib and induced the expression of CXCL9 and IFN-γ in a murine lung cancer model." (PMID 32138779, 2020).
lung cancer (continued). "A previous report demonstrated that the HDACi romidepsin enhances response to PD-1 blockade in lung cancer by inducing the expression of CCL5, CXCL9 and CXCL10, and thus enhancing T cells infiltration." (PMID 29371976, 2017). "We had previously shown that the depletion of either CXCL9 or CXCL10 inhibits antitumor responses in murine lung cancer, underscoring nonredundant functions of these cytokines in cancer immunity." (PMID 38518770, 2024). "Mirroring data in urothelial cells, we found that the pro-T cell cytokines CXCL9/10/11 are strongly induced by a combination of IFNγ and EZH2 inhibition in both human and murine tumoroids, and that this gene cluster is a direct PRC2 target in human lung cancer cells." (PMID 38265267, 2024). "In addition, we found lower cell motility in the CD8+ T cells in the patients with lung cancer compared to in healthy CD8+ T cells (p < 0.05), and there were decreased levels of CXCL9 and CXCL10 in the patient’s nonCD8+ PBMCs compared to healthy nonCD8+ PBMCs (p < 0.05)." (PMID 34680466, 2021). "Samples from lung cancer and NPC specimens not treated by primary antibody against CXCL9 were used as the positive and negative controls." (PMID 24278236, 2013).
vitiligo (48 papers, 2015 to 2025). Generalized well circumscribed patches of leukoderma that are generally distributed over symmetric body locations and is due to autoimmune destruction of melanocytes. "In mice, LEPTIN deficiency ameliorated the development of vitiligo and reduced the expression of Cxcl9, Gzmb, Ifng, and Mx1 in vitiligo lesions." (PMID 38421796, 2024). "Leptin deficiency also resulted in significantly lower expressed vitiligo-related genes, such as Cxcl9 (p = 0.0497), Gzmb (p < 0.001), Ifng (p = 0.0159), and Mx1 (p < 0.001) after modeling." (PMID 37207234, 2023). "CXCL9 was associated with the activity of vitiligo (p = 0.027)." (PMID 39981245, 2025). "Plasma IFN-γ, CXCL9, CXCL10, CXCL11 and IL-6 might be potential biomarkers for vitiligo recurrence, with CXCL9 also associated with disease activity." (PMID 39981245, 2025). "In conclusion, this study discovers that plasma IFN-γ, IFN-γ-regulated chemokines, including CXCL9, CXCL10 and CXCL11, and IL-6 might be potential biomarkers for vitiligo recurrence, with CXCL9 also associated with disease activity." (PMID 39981245, 2025). "In the context of autoimmune diseases such as vitiligo and cutaneous lupus erythematosus, the HSP 70–plasmacytoid dendritic cell–IFN-α–CXCL9/10 axis has been proposed as a key pathogenic mechanism." (PMID 40136446, 2025). "But a clinical study that included both segmental and non-segmental vitiligo patients, similar to our study, also showed that only serum CXCL9 levels correlated with vitiligo activity." (PMID 39981245, 2025). "Keratinocytes contribute significantly to vitiligo pathogenesis through secretion of chemokines such as CXCL9 and CXCL10, sustaining immune cell recruitment and inflammation." (PMID 40856249, 2025). "The CXCL9 level in patients with active vitiligo was significantly higher than patients with stable vitiligo (p = 0.027)." (PMID 39981245, 2025). "IFN-γ-induced signature has been observed in human skin with vitiligo, with the upregulation of cytokines CXCL9 and CXCL10 via JAK1/2." (PMID 38975347, 2024). "Patients with more active than stable vitiligo lesions showed higher baseline serum levels of CXCL9 and PD-L1, while patients with more stable than active lesions showed higher baseline serum levels of HO-1." (PMID 39023568, 2024). "A limited number of biomarkers has already been discovered for vitiligo through the discovery of the pathological role of the IFNγ-CXCL9/CXCL10-CXCR3 axis." (PMID 38715599, 2024). "More recent meta-analysis data show that CXCL9, CXCL10, CCL5, CXCL8 (IL-8), CXCL12, and CXCL16 can serve as diagnostic blood biomarkers for vitiligo." (PMID 38673994, 2024). "The JAK-STAT pathway is activated with IFN-γ as the crucial cytokine and Th1-associated chemokines such as CXCL9 and CXCL10 recruit immune cells towards vitiligo skin." (PMID 39274437, 2024). "CXCL9 has been extensively studied in vitiligo (497 vitiligo patients vs 257 healthy controls), although the data have been variable." (PMID 36911664, 2023). "The CXCL9/CXCL10-CXCR3 axis is closely involved in the progression of vitiligo and deserves further attention." (PMID 37809065, 2023). "Proinflammatory FB populations have been recently described in other inflammatory skin diseases, including Th2 responsive COL6A5+COL18A1+ FBs in atopic dermatitis and T cell–attracting CXCL9/CXCL10-expressing FBs in vitiligo." (PMID 37471168, 2023). "4/11 studies mentioned increased CXCL9 concentration in the circulation of vitiligo patients compared to healthy controls." (PMID 36911664, 2023). "CXCL9 is overexpressed in vitiligo skin compared to healthy skin (5 studies: 2 blister fluid, 2 mRNA of the skin, 1 immunohistochemistry)." (PMID 36911664, 2023). "In both active and stable vitiligo, CXCL9 and CXCL10 were significantly higher than controls (p < 0.05)." (PMID 37762802, 2023).
vitiligo (continued). "Most vitiligo studies have concentrated on a small number of chemokines based on previous findings, as evidenced by the large number of studies on CXCL9 and CXCL10." (PMID 36911664, 2023). "A dramatic increase in CXCL9 concentrations in the actively progressing lesions compared to stable vitiligo skin became apparent from 2 studies (5.3-12.3 fold increase; 19 active vs 36 stable; concentrations in blister fluid)." (PMID 36911664, 2023). "Only 1/5 reports found elevated circulating CXCL9 levels in active compared to stable vitiligo patients, although the final results of studies investigating CXCL9 in blister fluid were borderline significant (P = 0.05)." (PMID 36911664, 2023). "ROC curve analysis of CXCL9 with disease severity in vitiligo is significant (AUC = 0.739, p = 0.0022)." (PMID 35464413, 2022). "This suggests that the contexts in which CXCL9/10 are produced in active and stable vitiligo are different." (PMID 35653192, 2022). "We demonstrate that stress keratinocytes communicate with adaptive immune cells via the CXCL9/CXCL10/CXCR3 axis to create local inflammatory loops that are active in stable vitiligo." (PMID 35653192, 2022). "CXCL10 is elevated substantially with active vitiligo compared to stable vitiligo, whereas CXCL9 of active vitiligo is significantly elevated compared to healthy controls but not stable vitiligo." (PMID 35464413, 2022). "Most studies on vitiligo have focused on active disease, and the importance of the CXCL9/CXCL10/CXCR3 axis is well established from studies on human skin samples." (PMID 35653192, 2022). "IFN-γ and its’ signature chemokines CXCL9 CXCL10 are critical in the pathogenesis of vitiligo for recruiting autoreactive cytotoxic T lymphocytes (CTLs)." (PMID 35464413, 2022). "In recent years, various studies have showed that the IFN-γ-CXCL9/10-CXCR3 axis appears to be important in vitiligo, via inhibiting melanogenesis, inducing apoptosis of melanocytes, and further recruiting T cells to the skin." (PMID 36119071, 2022). "Recent studies have shown that chemokine CXCL9 CXCL10 is elevated in the plasma of vitiligo patients with active vitiligo and correlated with treatment response." (PMID 35464413, 2022). "The upregulation of CXCL9 was first detectable in the new lesion of vitiligo, followed by increased levels of CXCL10." (PMID 35096274, 2022). "Among them, a lot of genes have been described to be involved in vitiligo, such as CXCL9, CCR6, and IL-33." (PMID 35406685, 2022). "The univariate analysis revealed that high expression of CXCL9 was a significant independent predictor of the ineffective treatment response to CMT in patients with vitiligo." (PMID 34521889, 2021). "In conclusion, the activity of vitiligo has a positive correlation with the levels of CXCL9 and CXCL10 in the blister fluid." (PMID 34521889, 2021). "We propose that managing the CXCL9 level in the blister fluid is the most reliable indicator to guide clinical therapy and choose the timing of transplantation for patients with vitiligo." (PMID 34521889, 2021). "This phenomenon may be due to the IFN-γ/TNF-α-CXCL9/10 pathway played a central role in mediating the overlapping autoimmune imbalances in vitiligo and thyroid diseases." (PMID 39286278, 2024). "Additionally, the researchers revealed that the activated IFNγ-responsive fibroblasts can recruit CXCR3+ T cells and interact with melanocytes by secreting chemokines CXCL9/CXCL10 in vitiligo lesions." (PMID 37809065, 2023). "Moreover, key mediators such as interferon-γ (IFN-γ), C-X-C chemokine ligand 9 (CXCL9) and 10 (CXCL10), as well as interleukin-15 (IL-15) are also implicated in etiology of vitiligo." (PMID 35884944, 2022). "The IFN-γ-CXCL9/10-CXCR3 axis may be crucial for vitiligo pathogenesis, contributing to disease progression by inhibiting melanogenesis, inducing apoptosis of melanocytes, and further recruiting T cells to the skin." (PMID 36119071, 2022).